RNU4-6P (RNA, U4 small nuclear 6, pseudogene)
Synonyms: U4; U4/8; formerly RNU4P6
Gene: Small nuclear RNA gene on chromosome X (16,875,146 to 16,875,267, reverse strand). Ensembl gene ENSG00000222736.
Homologues: Orthologues: chimpanzee U4 (100% identical), macaque U4 (94% identical), rat LOC120098419 (68% identical), rat LOC120096439 (67% identical), dog U4 (66% identical), guinea pig U4 (57% identical). Paralogues in human: U4 (67% identical), RNU4-39P (66% identical), RNU4-48P (63% identical), RNU4-5P (63% identical), RNU4-82P (63% identical), RNU4-25P (62% identical), RNU4-40P (62% identical), RNU4-74P (62% identical), RNU4-46P (61% identical), RNU4-9P (61% identical), RNU4-36P (60% identical), RNU4-72P (60% identical), and 82 more.